RFPL3 (ret finger protein like 3)
Description:
(Microbial infection) Stimulates the activity of Human Immunodeficiency Virus 1/HIV-1 pre-integration complex.
Synonyms: RNF120
Tractability: Antibody: the Human Protein Atlas places it where antibodies can reach.
Gene: Protein-coding gene on chromosome 22 (32,354,885 to 32,361,161, forward strand). Ensembl gene ENSG00000128276.
Subcellular location: Cytoplasm; Nucleus
Subcellular location (Human Protein Atlas): Nuclear speckles; Plasma membrane
Gene Ontology:
Molecular function: protein binding; ubiquitin protein ligase activity
Biological process: innate immune response; regulation of gene expression
Cellular component: cytoplasm; nucleus
Genetic constraint (gnomAD): Loss-of-function variants: 8 observed, 8.09 expected, observed/expected ratio (o/e) 0.99, 90% interval 0.58 to 1.7. That is too few expected variants to judge how well the gene tolerates losing a copy. Missense variants: 280 observed, 318.18 expected, observed/expected ratio (o/e) 0.88, 90% interval 0.8 to 0.97. Synonymous variants: 114 observed, 120.81 expected, observed/expected ratio (o/e) 0.94, 90% interval 0.81 to 1.1.
Homologues: Orthologues: chimpanzee RFPL3 (95% identical), macaque RFPL1 (91% identical). Paralogues in human: RFPL1 (92% identical), RFPL2 (88% identical), RFPL4A (51% identical), RFPL4AL1 (51% identical), RFPL4B (29% identical), RNF135 (17% identical), SPRYD4 (10% identical), CD86 (7% identical), RNF152 (6% identical), CD274 (6% identical), PDCD1LG2 (6% identical), CD80 (5% identical).
Diseases named in the same sentence as RFPL3 in open-access papers:
RFPL3 is named in the same sentence as 6 diseases in open-access papers, as found by Europe PMC text mining. Sharing a sentence is not in itself a finding about the gene and the disease. The quoted sentences say what the papers report.
lung carcinoma (4 papers, 2014 to 2022). "Furthermore, the overexpression of RFPL3 was found to be significantly associated with lymph node metastasis of lung cancers and shorter OS of patients with lung adenocarcinomas." (PMID 26318425, 2015). "To clarify the role of hTERT in IPO13-mediated NSCLC cell growth, which is transcriptionally regulated by RFPL3 in lung cancer, we first measured hTERT expression at protein and mRNA levels in A549 and H1299 cells." (PMID 33082305, 2020). "In our current study, we provide the first evidence that IPO13, as a nucleocytoplasmic shuttling protein, is involved in RFPL3 translocation from the cytoplasm to the nucleus in lung cancer cells." (PMID 33082305, 2020). "Our previous studies have reported that RFPL3 protein exerts its unique function as a transcriptional factor of hTERT promoter after being transported into the lung cancer cell nucleus." (PMID 33082305, 2020). "Correspondingly, in vivo experiments again demonstrated that IPO13 promotes the progression of lung cancer by mediating RFPL3’s nuclear translocation and upregulation of hTERT expression." (PMID 33082305, 2020). "IPO13 interacted with RFPL3 in lung cancer cells, and the knockdown of IPO13 led to the cytoplasmic accumulation of RFPL3, the decreased anchoring of RFPL3 at hTERT promoter, and the downregulation of hTERT expression." (PMID 33082305, 2020). "Presently, in our study, we aimed to identify the molecular mechanism that mediates the nuclear translocation of RFPL3 in lung cancer." (PMID 33082305, 2020). "In summary, our paper exposes a novel pathway by which IPO13 facilitates the nuclear entry of RFPL3, which acts as a specific transcription factor of hTERT to control its expression and to be further involved in lung cancer development." (PMID 33082305, 2020). "The binding of RFPL3 to hTERT promoter was reduced markedly when CBP was knocked down by its specific siRNA or suppressed by its inhibitor in lung cancer cells with stable overexpression of RFPL3." (PMID 26318425, 2015). "Human lung cancer H1299, H322, H460 and A549 cells grown on chamber slides were cultivated for 24 hours, and the sub-cellular localization of RFPL3 and CBP and their co-localization were examined with a confocal microscope." (PMID 26318425, 2015). "Immunohistochemical analysis of tissue microarrays of lung cancers revealed the simultaneous overexpression of both RFPL3 and CBP predicted relatively poor prognosis." (PMID 26318425, 2015). "Our study will reveal a new activated mechanism of hTERT regulation in lung cancer cells and explore the RFPL3/CBP/hTERT signaling as a potential target for lung cancer treatment." (PMID 26318425, 2015). "We incubated the nuclear extracts from different lung cancer cells with anti-RFPL3 antibody, and the acetylation level of RFPL3 was tested using an anti-acetylation antibody." (PMID 26318425, 2015). "Conversely, inhibition of CBP activity by its specific inhibitor C646 attenuated the acetylation level of RFPL3, suggesting that CBP mediated the tumor-specific acetylation of RFPL3 and further interacted with each other in lung cancer cells." (PMID 26318425, 2015). "We also showed that the inhibition of RFPL3 expression significantly suppressed lung cancer cell growth in vitro and in a xenograft mouse model in vivo." (PMID 26318425, 2015). "The expression of RFPL3 protein kept nearly unchanged in lung cancer cells transfected with CBP plasmids." (PMID 26318425, 2015). "In this study, we used this systematic approach to pull down the potential hTERT promoter-binding proteins in lung cancer cells and identified the one as ret finger protein-like 3 (RFPL3)." (PMID 25481043, 2014). "We transfected the RFPL3-specific siRNA into lung cancer cell lines (A549 and H1299) which express high levels of RFPL3." (PMID 25481043, 2014). "More RFPL3 proteins bound to the hTERT promoter in lung cancer cells (H1299, A549), but the binding was very weak in lung normal cells (WI-38, HBE)." (PMID 25481043, 2014).
lung carcinoma (continued). "The high hTERT promoter-binding activity of RFPL3 was detected in lung cancer cells compared to normal cells." (PMID 25481043, 2014). "In this study, we identified ret finger protein-like 3 (RFPL3) as a hTERT promoter binding protein in lung cancer cells." (PMID 25481043, 2014). "The candidate lung cancer-specific hTERT promoter-binding protein (arrow) was predicted to be ret finger protein-like 3 (RFPL3)." (PMID 25481043, 2014). "Previous research has reported that RFPL-3 could activate the hTERT promoter and promote the growth of human lung cancer cells, especially in coordination with CBP." (PMID 35711680, 2022). "A previous study showed that RFPL-3 could bind to the hTERT promoter and reactivate telomerase activity in lung cancer cells." (PMID 35711680, 2022). "Previous research has reported a synergistic effect of CBP and RFPL-3 in lung cancer." (PMID 35711680, 2022). "Regarding the finding that RFPL3 localized in the nucleus in lung cancer cells, we speculate that IPO13 might participate in the nucleocytoplasmic transport of RFPL3." (PMID 33082305, 2020). "Based on the common transcriptional regulatory function of CBP, we proposed that it might be a helper of RFPL3 in mediating hTERT activation in lung carcinoma." (PMID 26318425, 2015). "In our previous study, we discovered and identified RFPL3 as a novel hTERT promoter-binding protein which could upregulate hTERT activity in lung cancers." (PMID 26318425, 2015). "The results showed that CBP was found in all the lung cancer cell lines in the complexes pulled down by anti-RFPL3 antibody, but not found in the IgG-treated samples, indicating that RFPL3 indeed interacted directly with CBP in the nucleus of lung cancer cell lines." (PMID 26318425, 2015). "We next investigated the effect of CBP on RFPL3-mediated telomerase activity in lung cancer cells." (PMID 26318425, 2015). "Since RFPL3 and CBP are overexpressed in lung cancer cells, a possible association between these two proteins might exist." (PMID 26318425, 2015). "Previously, we identified RFPL3 as a new transcription activator of hTERT in lung cancers." (PMID 26318425, 2015). "Collectively, our results reveal a new mechanism of hTERT regulation in lung cancer cells and suggest the RFPL3/CBP/hTERT signaling pathway may be a new targets for lung cancer treatment." (PMID 26318425, 2015). "To further assess whether RFPL3 is a potential target for lung cancer, we also evaluated tumorigenicity using a xenograft mouse model." (PMID 25481043, 2014). "We also determined whether RFPL3 functions in lung cancer cells by interacting with other transcription factors such as AP-2, an important protein which controls the expression of hTERT." (PMID 25481043, 2014). "Thus, the identification of such molecular mechanism involved in the subcellular distribution of RFPL3 in lung cancer cells might provide a new potential target for anticancer therapies." (PMID 33082305, 2020). "Furthermore, our in vitro and in vivo results revealed that RFPL3 knockdown inhibited lung cancer cell growth and the genetic–clinicopathologic correlation analysis found that upregulation of RFPL3 was significantly associated with shorter OS of patients with lung adenocarcinomas." (PMID 25481043, 2014). "To further investigate the involvement of hTERT expression in RFPL3 knockdown-mediated lung cancer cell proliferation suppression, we rescued hTERT expression using an hTERT-expressing lentivirus to infect the lung cancer cell lines stably expressing RFPL3 shRNA." (PMID 25481043, 2014). "In addition, we also detected the interaction between RFPL3 and AP-2 proteins in lung cancer cells." (PMID 25481043, 2014). "Since RFPL3 has been shown to be an hTERT promoter binding protein and it interacts with CBP in lung cancer cells, we next analyzed the effect of CBP on the RFPL3-mediated hTERT transcriptional activation." (PMID 26318425, 2015).
lung carcinoma (continued). "Since hTERT was approved to be involved in the growth of lung cancer cells, and RFPL3 and CBP had been shown to be able to up-regulate hTERT expression, we next tested the coordinated effect of RFPL3 and CBP on cell proliferation in lung cancer cells." (PMID 26318425, 2015). "In this study, we found that RFPL3 colocalized and interacted directly with CBP in the nucleus of lung cancer cells." (PMID 26318425, 2015). "The RFPL3 and CBP expression in different lung cancer cell nucleus was also determined by Western blot assay." (PMID 26318425, 2015). "Consistency of distribution is a prerequisite for the interaction, and duel-luciferase assay gives us another evidence that RFPL3 and CBP are colocalized in the nucleus of lung cancer cells." (PMID 26318425, 2015). "The simultaneous overexpression of RFPL3, CBP and hTERT predicted relatively poor prognosis of lung cancer patients, suggesting the most potential significance to inhibit lung cancer cell growth by downregulating the RFPL3/CBP/hTERT signaling pathway." (PMID 26318425, 2015). "We found that the overexpression of RFPL3 in normal lung cell lines (WI-38 and HBE) and lung cancer cell lines (A549) significantly increased the levels of hTERT mRNA and protein expression and the activity of telomerase." (PMID 25481043, 2014). "In addition, Western blot and densitometric analysis showed that RFPL3, CBP and hTERT were overexpressed in lung cancer cell lines (H1299, H460, H322, A549) compared with the normal lung cell lines (HLF)." (PMID 26318425, 2015). "We thus speculated that RFPL3 may cooperate with CBP to regulate hTERT transcription and telomerase activity in lung cancer." (PMID 26318425, 2015). "Although CBP has been shown to up-regulate the expression of many cancer-related genes, it was interesting to discover that CBP could not regulate RFPL3 expression itself in human lung cancer cells from our results." (PMID 26318425, 2015).
lung adenocarcinoma (2 papers, 2014 to 2015). A carcinoma that arises from the lung and is characterized by the presence of malignant glandular epithelial cells. "We demonstrate here that high level of RFPL3 protein expression in tumor cells is associated with lymph node metastasis and poor outcome in patients with lung adenocarcinoma." (PMID 25481043, 2014). "For the 100 lung adenocarcinoma cases, 23 cases showed high expression of RFPL3 and CBP, in which an average of 78% owned positive high hTERT staining." (PMID 26318425, 2015). "Both high expression of CBP and RFPL3 predicted a shorter overall survival time in patients with lung adenocarcinomas compared with those with dual low expression of these two proteins (P < 0.001, log-rank test)." (PMID 26318425, 2015). "We further analyzed the synergistic effect of CBP, RFPL3 and hTERT expression on the survival rate of patients with lung adenocarcinomas by Kaplan–Meier analysis." (PMID 26318425, 2015). "Further detailed analyses are necessary to determine the partner transcription factors of RFPL3 on hTERT expression activation in lung adenocarcinomas." (PMID 25481043, 2014). "In summary, our findings show that RFPL3 is a novel hTERT promoter regulating protein and plays an important role in the hTERT overexpression and tumor growth in lung adenocarcinomas." (PMID 25481043, 2014). "Immunohistochemical analysis of 181 human lung adenocarcinomas specimens showed a significant correlation between RFPL3 and hTERT expression." (PMID 25481043, 2014). "Here, for the first time, we showed that the increased abundance of RFPL3 protein is another potential molecular mechanism for the up-regulated hTERT expression in some lung adenocarcinomas by supporting both clinical and mechanistic evidence." (PMID 25481043, 2014). "The expression of RFPL3 and hTERT proteins was further analyzed in 181 primary human lung adenocarcinoma tissues by IHC using tissue micro arrays." (PMID 25481043, 2014). "The expression status and clinical significance of RFPL3 in lung adenocarcinomas was also investigated." (PMID 25481043, 2014). "In the 181 human lung adenocarcinoma tissues, there was a positive correlation between the levels of RFPL3 protein and hTERT protein (P < 0.001, χ2 tests)." (PMID 25481043, 2014). "Multivariate analysis further indicated that RFPL3 upregulation (P = 0.001) and presence of lymph node metastasis (P = 0.002) were 2 independent prognostic predictors for OS in patients with lung adenocarcinoma enrolled in this study." (PMID 25481043, 2014). "Our results showed that the overexpression of RFPL3 protein was in 45% of primary lung adenocarcinomas." (PMID 25481043, 2014). "We scored the immunohistochemical staining of RFPL3 and hTERT in the human lung adenocarcinoma specimens by multiplying the intensity and the percentage value (the range of this calculation was therefore 0–12) and then analyzed the scores." (PMID 25481043, 2014). "Survival analyses showed that high expression of RFPL3 significantly correlated with shorter overall survival time in patients with lung adenocarcinomas (P < 0.001, log-rank test)." (PMID 25481043, 2014). "Based on univariate analysis, the up-regulation of CBP and RFPL3 (P < 0.001), T3 stage (P = 0.045) and presence of lymph node metastasis (P= 0.016) were significant inferior prognostic factors for OS in patients with lung adenocarcinoma." (PMID 26318425, 2015). "Thus, for the first time, our report describes a novel molecular mechanism by which RFPL3 promotes hTERT transcription and expression in lung adenocarcinomas." (PMID 25481043, 2014). "Because we observed that there were 25 tumors that contained high levels of hTERT and low levels of RFPL3 in our study, indicating that other factors, in addition to the RFPL3, may be involved in the upregulation of hTERT in lung adenocarcinomas." (PMID 25481043, 2014).
lung adenocarcinoma (continued). "Since RFPL3 plays a positive role in the activation of hTERT expression and telomerase activity, we reasoned that RFPL3 may be a potential therapeutic target in lung adenocarcinoma treatment." (PMID 25481043, 2014). "By univariate analysis, RFPL3 upregulation (P < 0.001), T3 stage (P = 0.008) and presence of lymph node metastasis (P < 0.001) were significant inferior prognostic factors for OS in patients with lung adenocarcinoma." (PMID 25481043, 2014). "Moreover, the lung adenocarcinoma patients with high RFPL3 and hTERT expression had a significantly shorter OS than those with low RFPL3 and hTERT expression (P < 0.001, log-rank test)." (PMID 25481043, 2014). "Our results suggest that RFPL3 might be a potential therapeutic target in lung adenocarcinomas." (PMID 25481043, 2014). "However, the exact molecular mechanism responsible for RFPL3 overexpression in lung adenocarcinoma cells is still unknown." (PMID 25481043, 2014). "The expression of RFPL3, CBP and hTERT protein was analyzed in lung tumor tissues from 100 cases of patients with lung adenocarcinoma by immunohistochemical assay based on tissue microarrays." (PMID 26318425, 2015). "We first determined the expressions of RFPL3, CBP and hTERT in the fresh tumor specimens and their matched adjacent lung tissues (distance from tumor over 3 cm) from 5 cases of lung adenocarcinoma patients by Western blot analysis." (PMID 26318425, 2015). "The potential positive correlation between the expression of RFPL3, CBP and hTERT in lung adenocarcinoma tissues were shown." (PMID 26318425, 2015). "The staining level of RFPL3, CBP and hTERT in the human lung adenocarcinoma specimens was scored by multiplying the intensity and the percentage value with a range from 0–12 and then the scores were analyzed." (PMID 26318425, 2015). "Moreover, the lung adenocarcinoma patients with simultaneously high expression of CBP, RFPL3 and hTERT had a significantly shorter OS than those with low CBP, RFPL3 and hTERT expression (P < 0.001, log-rank test)." (PMID 26318425, 2015).
lymph node metastasis (2 papers, 2014 to 2015). "The results showed that RFPL3 upregulation was significantly associated with lymph node metastasis (P < 0.001, χ2 tests)." (PMID 25481043, 2014). "The overexpression of RFPL3 was also associated significantly with lymph node metastasis." (PMID 25481043, 2014). "The up-regulation of CBP and RFPL3 had no significantly association with patient's gender (P = 0.554, χ2 tests), age (P = 0.861, χ2 tests), T classification (P = 0.179, χ2 tests) and lymph node metastasis (P = 0.075, χ2 tests)." (PMID 26318425, 2015).